NKX6-3 (NK6 homeobox 3)
Description:
Putative transcription factor, which may be involved in patterning of central nervous system and pancreas.
Synonyms: FLJ25169; NKX6.3
Tractability: No criterion of Open Targets' tractability assessment is met for any kind of drug.
Gene: Protein-coding gene on chromosome 8 (41,645,177 to 41,650,817, reverse strand). Ensembl gene ENSG00000165066.
Subcellular location: Nucleus
Gene Ontology:
Molecular function: DNA-binding transcription activator activity, RNA polymerase II-specific; DNA-binding transcription repressor activity, RNA polymerase II-specific; RNA polymerase II cis-regulatory region sequence-specific DNA binding; sequence-specific DNA binding; sequence-specific double-stranded DNA binding; DNA-binding transcription factor activity, RNA polymerase II-specific; DNA binding
Biological process: negative regulation of transcription by RNA polymerase II; positive regulation of transcription by RNA polymerase II; cell differentiation; regulation of transcription by RNA polymerase II; regulation of DNA-templated transcription
Cellular component: chromatin; nucleus
Genetic constraint (gnomAD): Loss-of-function variants: 17 observed, 20.56 expected, observed/expected ratio (o/e) 0.83, 90% interval 0.56 to 1.24. The upper end of that interval is the gene's LOEUF score, 1.24, which puts it in group 5 of 6, group 1 being the genes least tolerant of losing a copy. Missense variants: 363 observed, 343.81 expected, observed/expected ratio (o/e) 1.06, 90% interval 0.97 to 1.15. Synonymous variants: 177 observed, 160.43 expected, observed/expected ratio (o/e) 1.1, 90% interval 0.98 to 1.25.
Homologues: Orthologues: chimpanzee NKX6-3 (99% identical), mouse Nkx6-3 (94% identical), rat Nkx6-3 (94% identical), rabbit NKX6-3 (93% identical), pig NKX6-3 (92% identical), dog NKX6-3 (92% identical), guinea pig NKX6-3 (92% identical), macaque NKX6-3 (73% identical), zebrafish nkx6.3 (64% identical), tropical clawed frog nkx6-3 (58% identical), Drosophila melanogaster HGTX (39% identical), Drosophila melanogaster NK7.1 (35% identical), and 5 more. Paralogues in human: NKX6-1 (51% identical), NKX6-2 (50% identical), NKX1-1 (22% identical), NKX1-2 (20% identical), NKX2-1 (17% identical), NKX2-4 (17% identical), NKX2-2 (16% identical), NKX2-3 (16% identical), NKX2-5 (16% identical), NKX3-1 (16% identical), NKX3-2 (16% identical), NKX2-6 (15% identical), and 1 more.
Diseases named in the same sentence as NKX6-3 in open-access papers:
NKX6-3 is named in the same sentence as 17 diseases in open-access papers, as found by Europe PMC text mining. Sharing a sentence is not in itself a finding about the gene and the disease. The quoted sentences say what the papers report.
gastric cancer (10 papers, 2015 to 2025). A primary or metastatic malignant neoplasm involving the stomach. "Aberrant downregulation of NKX6-3 causes gastric cancer, indicating tumour suppressor activity in this tissue type." (PMID 41153416, 2025). "When we compared the transcriptomic profiles of the two infected genotypes, 76 genes, including gastric cancer tumor suppressors involved in the Wnt/β-catenin signaling pathway (Esrrg, Nkx6-3), were upregulated by Smox deletion." (PMID 39523394, 2025).
diffuse large B-cell lymphoma (4 papers, 2018 to 2025). "Here, we introduce the NKL-code in normal hematopoiesis and focus on deregulated NKL homeobox genes in B-cell lymphoma, including HLX, MSX1 and NKX2-2 in Hodgkin lymphoma; HLX, NKX2-1 and NKX6-3 in diffuse large B-cell lymphoma; and NKX2-3 in splenic marginal zone lymphoma." (PMID 31779217, 2019). "In contrast, NKX6-3 is highly expressed in TCF3-subtype BCP-ALL and GC-B-cell-derived diffuse large B-cell lymphoma subsets, contrastingly indicating oncogene activity in developing B-cells." (PMID 41153416, 2025). "Based on these findings we performed detailed studies of the B-cell specific NKL homeobox gene NKX6-3 which showed enhanced activity in patient subsets of follicular lymphoma, mantle cell lymphoma and diffuse large B-cell lymphoma (DLBCL), and in three DLBCL cell lines to serve as in vitro models." (PMID 30308041, 2018). "Thus for example, NKX2-1 is ectopically expressed in diffuse large B-cell lymphoma (DLBCL), and the hematopoietic NKL homeobox genes NKX2-3 and NKX6-3 are overexpressed while MSX1 is downregulated in particular B-cell lymphomas." (PMID 30680064, 2018).
B-cell lymphoma (3 papers, 2018 to 2019). "NKX6-3 is physiologically expressed in B-cell differentiation and aberrantly overexpressed in B-cell lymphomas." (PMID 30308041, 2018). "Of note, NKL homeobox genes HLX, NKX2-1, NKX2-3, NKX6-3 and MSX1 are deregulated in B-cell lymphoma and show aberrant activity in T-ALL as well which might indicate similar oncogenic functions in both lineages of lymphoid malignancies." (PMID 29581848, 2018).
lung carcinoma (2 papers, 2022 to 2025). "This regulatory link may inhibit NKX6-3 expression indirectly and has also been reported in lung cancer cells." (PMID 41153416, 2025). "For instance, promoter regions of Human kallikrein 2(KLK2) in prostate, Apolipoprotein A1 (APOA1) in liver, NK6 homeobox 3 (NKX6.3) in stomach, paired box gene-8 (PAX-8) in kidney, and Surfactant Protein B (SFTPB) in lung cancers were among the selected markers from our pipeline." (PMID 35729208, 2022).
leukemia (1 paper, 2025). A malignant (clonal) hematologic disorder, involving hematopoietic stem cells and characterized by the presence of primitive or atypical myeloid or lymphoid cells in the bone marrow and the blood. "Finally, public RNA-seq data from 93 leukemia cell lines for the identified NKX6-3 target genes show reduced activity of CD109 and overexpression of GP5 and MPP7 in RCH-ACV and MHH-CALL-3, highlighting the suitability of these cell lines as models for their investigation in follow-up studies." (PMID 41153416, 2025).
lymphoid leukemia (1 paper, 2019). A malignant lymphocytic neoplasm of B-cell or T-cell lineage involving primarily the bone marrow and the peripheral blood. "This relationship has also been shown for MSX1 and NKX6-3 in lymphoid leukemia/lymphoma." (PMID 31825998, 2019).
tumor (10 papers, 2015 to 2025). "Thus, NKX6-3 may perform tumor suppressor activity in ABC-DLBCL as well." (PMID 31141539, 2019).
NKX6-3 also shares sentences with these, for which no sentence is quoted: cancer (8 papers); gastric tumor (2); lymph node metastasis (2); Atrophy (1); follicular lymphoma (1); Hodgkins lymphoma (1); lymphoma (1); mantle cell lymphoma (1); splenic marginal zone lymphoma (1); type 2 diabetes (1).